NOS2 (nitric oxide synthase 2)
Diseases named in the same sentence as NOS2 in open-access papers (continued):
Sharing a sentence is not in itself a finding about the gene and the disease.
breast carcinoma (continued). "Given that inflammation is commonly encountered in breast cancers, the poor prognosis predicted by increased tumor expression of NOS2 and/or COX2 may in part be due to an altered tumor immune microenvironment that limits treatment efficacy and clinical outcome." (PMID 38912586, 2024). "In addition, NOS has been reported to be associated with resistance to cisplatin and 5-fluorouracil through Wnt signaling and family with sequence similarity 171, member B in non-small cell lung cancer, breast cancer, and leukemia; but this is a report of drug resistance regulated by NOS2." (PMID 31195721, 2019). "Earlier studies identified NOS2 and COX2 feedforward signaling that supports many oncogenic pathways in ER− breast cancer." (PMID 39356141, 2024). "The combination of low SerpinB2, high NOS2, and low CD206 expression was favorable for survival in patients with breast cancer, as assessed in the BreastMark dataset." (PMID 38956496, 2024). "The combination of SerpinB2, NOS2, and CD206 expression in tumor cells as well as TAMs and its clinical significance should be further evaluated in a cohort of patients with breast cancer." (PMID 38956496, 2024). "TCGA pathway analysis of NOS2/COX2+ tumors implicates many immune pathways, including IL-17A, IFN-γ, IL-1β, and TLR signaling in ER– breast cancer." (PMID 38912586, 2024). "NOS2 and COX2 expression have prognostic values in ER- breast cancer with hazard ratios (HR) of 6 and 2.72, respectively." (PMID 38892290, 2024). "Breast cancer patients that had been given radiotherapy were selected from The Cancer Genome Atlas (TCGA) and separated based on their expression of NRP2 and NOS2 mRNA." (PMID 39352757, 2024). "CD44 mRNA expression was induced following chronic exposure to 300 μM DETANO and is consistent with induced expression in high NOS2 expressing ER- breast tumors and NO-induced CD44 protein expression in TNBC breast cancer cells." (PMID 36830680, 2023). "As expected, seven of the TME prognostic genes (NOS2, SCG2, RGS3, EMP1, PDLIM4, PCDH9, and GFI1) showed dual functions in breast cancer progression." (PMID 36936167, 2023). "In tumors of BALB/c mouse breast cancer model, decrease in the average amount of TAMs and the number of M2-like F4/80+CD206+ TAMs and a significant increase in the number of M1-like F4/80+Nos2+ TAMs were observed after the treatment with endostatin." (PMID 34209679, 2021). "Is it noteworthy that NOS2, which was upregulated on Col1 substrates according to DNA microarray gene expression data, increase EMT in breast cancer cells." (PMID 26713616, 2015). "One interesting gene that was upregulated was Nitric oxide synthase 2 (NOS2) (2.6-fold), which has been shown to activate beta-catenin and EMT in breast cancer cells." (PMID 26713616, 2015). "In summary, this work identifies a novel combination of molecular targets involved in NOS2/TIMP-1/Akt pro-survival signaling, which influence breast cancer outcome within a specific tumor subpopulation." (PMID 22957045, 2012). "Spatial clustering of NOS2+ and COX2+ tumor phenotypes determines survival in ER– breast cancer." (PMID 40663402, 2025). "In estrogen receptor–negative (ER–) breast cancer, in particular, elevated NOS2/COX2 levels are strongly predictive of poor prognosis." (PMID 40663402, 2025). "The analyses of the combinations of SerpinB2/NOS2, SerpinB2/CD206, and NOS2/CD206 groups, as well as the individual expressions of SerpinB2, NOS2, or CD206 alone did not demonstrate a significant difference in the DFS of patients with breast cancer." (PMID 38956496, 2024).
breast carcinoma (continued). "Seven of the 15 TME prognostic genes (NOS2, SCG2, RGS3, EMP1, PDLIM4, PCDH9, and GFI1) were involved in enhancing cell proliferation, destroying cell apoptosis, promoting cell invasion, or migration in breast cancer." (PMID 36936167, 2023). "Meanwhile, the overexpression of linc00514 in breast cancer cells inhibited the THP-1 mRNA levels of TNF-α, NOS2, and IL-6, which are M1 polarization markers of macrophages, while it promoted the expression of Arg-1 at both mRNA and protein levels, which is a M2 polarization marker." (PMID 32943090, 2020). "Furthermore, the interference of STAT3 (the transfection of si-STAT3) in linc00514-OVE breast cancer cells elevated the mRNA levels of TNF-α, NOS2, and IL-6, and reduced the expression of Arg-1 at both mRNA and protein levels." (PMID 32943090, 2020). "Furthermore, our data showing that NO results in a MEK/ERK/Ets-1 signaling cascade in ER-/HER2+ SKBR3 cells suggest that high NOS2 expression and NO signaling may induce proliferative and aggressive phenotypes in HER2+ breast cancer." (PMID 22971289, 2012). "NOS2 and COX-2 co-expression establishes a positive feed-forward loop, driving immunosuppression and metastasis in estrogen receptor-negative (ER-) breast cancer." (PMID 38892290, 2024). "Recently, elevated tumor nitric oxide synthase 2 (NOS2) and COX2 coexpression has shown strong predictive power, in which their elevated expression correlates with reduced survival in ER− but not ER+ breast cancer." (PMID 39356141, 2024). "Similar results were seen for the M1 markers Nos2 and Tnfa after culturing RAW264.7 cells with CM from 66Cl-4 mammary carcinoma cells without or with miR-200c." (PMID 34045467, 2021). "The increase of iNOS (inducible NOS, also known as NOS2) is correlated with a decreased survival of ER negative and basal-like breast cancer (BC) patients." (PMID 30155439, 2018).
colitis (43 papers, 2011 to 2026). Inflammation of the colon. "Mice treated with fucoidan exhibited significant protection from colitis, evidenced by longer colonic length, less weight loss, and lower expression levels of inflammatory genes such as Il‐1b, Il‐18, Il‐6, Nos2, and Tnfα." (PMID 40545965, 2025). "To further confirm the relationship between LPS/TLR4 and TNFα/NOS2 induction, as well as the role of NF-κB signaling in ulcerative colitis and colitis associated tumorigenesis, we used ex vivo experiments." (PMID 28408791, 2017). "Furthermore, NO production was increased in a mouse model of colitis, and the dysregulation of intestinal ion transport was caused by increased inducible NO synthase (NOS2) synthesis in enteric glia." (PMID 37551711, 2024). "To further investigate whether the severity of colitis in Fam76b knockout mice was related to the upregulated M1 macrophage polarization caused by FAM76B, we detected the expression of NOS2 in the colonic tissues of wild-type and Fam76b knockout mice with colitis." (PMID 38421448, 2024). "Stress exacerbated disease severity in both infectious (C. rodentium) and chemically induced (DSS) colitis, amplifying colonic expression of Duox2, Nos2, and Ccl2, especially." (PMID 41418891, 2025). "Macrophage TIM3 can inhibit the expression of proinflammatory cytokines such as TNFα, IL-1β, IL-6, IL-12, and NOS2 in dextran sodium sulfate (DSS)-induced colitis." (PMID 41307843, 2025). "The results demonstrated that the quantity of F4/80+NOS2+M1 macrophages in the colon tissue of Fam76b knockout mice with colitis was significantly increased in contrast with wild-type mice with colitis." (PMID 38421448, 2024). "Clinical datasets of inflammatory diseases revealed that the gene expression of HIF-1α and NOS2 are correlated in several diseases, like colon inflammation, Crohn’s disease, and mixed osteosarcoma." (PMID 37965321, 2023). "Further study is required to unravel the link between UCC118TM and Nos2 and determine if Nos2 is involved in the beneficial effects of UCC118TM in colitis." (PMID 35889102, 2022). "NOS2 gene expression was significantly decreased in the Jatrorrhizine-treated compared to the untreated DSS-induced colitis (P < 0.05)." (PMID 36271438, 2022). "Once activated, both β-catenin and NF-kB transactivate many common target genes such as Ptges2, Nos2 and Ccnd1 and respective protein levels [COX2, inducible-NOS (iNOS) and Cyclin D1] with established roles in the development of colitis and CAC." (PMID 36584137, 2022). "SOCS2−/− mice showed higher disease activity during colitis with increased mRNA expression of the pro-inflammatory cytokines nitric oxide synthase 2 (NOS2) and interleukin 1 β (IL1-β)." (PMID 32349250, 2020). "Together, these results demonstrate that TTP in IECs targets Nos2 expression and aggravates acute colitis." (PMID 31595002, 2019). "Our findings are in agreement with previous data showing the overexpression of TNF-α and NOS2 in the inflamed intestinal mucosa in UC patients, human colon carcinoma tissue, and murine model of carcinoma arising on colitis." (PMID 28408791, 2017). "Consistent with antimicrobial activity in the lumen of the gut during colitis, we observed significantly higher expression of the AMPs S100a8, S100a9, S100a14 and Ltf as well as Nos2 in colon contents." (PMID 27003245, 2016). "Our present data corroborated with this observation by demonstrating that DSS-induced colitis increased NOS2 and VEGF expression." (PMID 22073270, 2011). "Blocking NOS2 expression using gene knockout or specific inhibitors ameliorates the severity of experimental colitis." (PMID 22073270, 2011). "Collectively, our study results showed, for the first time, that jatrorrhizine alleviates DSS-induced colitis via regulating the composition of gut microbiota in colitis mice, affecting the ribosome signaling pathway, and reducing the expression of the NOS2 gene." (PMID 36271438, 2022).
colitis (continued). "We measured the gene expression of the pro-inflammatory cytokines nitric oxide synthase 2 (NOS2) and interleukin 1 β (IL-1β), as well as the anti-inflammatory interleukin-4 (IL-4) cytokine, in colonic tissues before and after induction of colitis and during recovery." (PMID 32349250, 2020). "Additionally, there is notable upregulation in the mRNA expression of Nos2 in the experimental colitis group in respect to control group." (PMID 33061833, 2020). "We also show that mice producing NOS2 in IECs fare better in a model of experimental colitis." (PMID 31595002, 2019). "Decline in mRNA expression of Nos2 after G-1 treatment in TNBS-induced colitis was noted." (PMID 31043642, 2019). "While Nos2 may contribute to these phenotypes or provide an additional defense against severe DSS colitis, we cannot eliminate the possibility that other TTP target genes also contribute." (PMID 31595002, 2019). "In addition, in vitro atRA treatment of inflamed colonic mucosa from patients with ulcerative colitis and colitis-associated cancer modulates the LPS/TLR4/NFκB signaling pathway and decreases nitric oxide synthase 2 (NOS2) and TNF-α expression." (PMID 30158832, 2018). "Our findings suggest that the effect of OPN on NOS2 expression in macrophages might be context-specific and dependent on the phase of colitis." (PMID 26274807, 2015). "The lower Nos2 expression in the DSS group might suggest a shift of arginine metabolism towards Arg1 during colitis resulting in higher levels of the wound healing-promoting polyamines, proline and ornithine, and lower levels of nitric oxide and free radicals, consistent with M2 activation." (PMID 31882991, 2019). "As IL-1β, Tnf-α, and Nos2 expression was elevated in ETBF-infected muMT mice compared with ETBF-infected WT mice, the up-regulation of innate immune responses in ETBF-infected muMT mice could contribute to the persistent colitis in B-cell-deficient mice, which needs further study." (PMID 38203534, 2023). "Recent studies have highlighted that the role of Nos2 in the context of colitis is complex, with Nos2 activity being beneficial for epithelial homeostasis as well as during DSS colitis." (PMID 35889102, 2022). "One week after induction of colitis, rats were assessed by MRC, colon histopathology and inflammation markers (Interleukin 1β, Tumor necrosis factor α, Nitric Oxide Synthase 2 and Cyclooxygenase 2)." (PMID 34735489, 2021). "Although clinical and experimental investigations have shown that the inducible isoform of NOS, NOS2, is expressed in the inflamed mucosa in IBD patients or in animals with experimental colitis, the role of NO in colitis remains a subject of controversy." (PMID 30972302, 2019). "In a dextran sulfate sodium (DSS)-induced colitis model mice, LBP (intragastrica (i.g.), 200 mg/kg) could suppress the expression of the M1 macrophage marker nitric oxide synthase 2 (NOS2) while promoting the expression of the M2 marker arginase 1 (Arg-1)." (PMID 41050703, 2025). "Previous studies have shown that TLR-2 and NOS-2 expression decreases with anti-inflammatory therapies and that the dysregulation or deletion of these genes is crucial for both IBD pathogenesis and attenuation of DSS induced colitis severity in mice." (PMID 39275347, 2024). "Nevertheless, BM-MSC treatments downregulated Nos2, Arg1, Gata3, Mrc1 and Hmox1 which were upregulated in Winnie mice and IBD patients; but are reportedly also upregulated by MSCs in chemical models of colitis." (PMID 38503815, 2024). "Given our results that TTP negatively regulates Nos2, we predicted that ΔIEC mice may display an altered response to DSS colitis." (PMID 31595002, 2019).
colitis (continued). "These latter correlations were maintained mainly in females, who additionally displayed a strong positive correlation with Vegfa and Tjp1, and a negative correlation with Nos2 in therapeutic DSS-colitis and positive ones with Nos2 and Tnfa in preventive TNBS-colitis." (PMID 37047397, 2023). "In the preventive trial with DSS-colitis, dexamethasone-induced an increase in Hif1a and Il6, and a decrease in Tjp1 expression compared to controls, while Tgfb1 and Vegfa expression was increased in the MTADV group, as well as Nos2 and Tjp1 in comparison to dexamethasone." (PMID 37047397, 2023). "Finally, note that the TNBS colitis model also showed strong negative correlations between SAA and Il6 in females and Vegfa or Nos2 in males." (PMID 37047397, 2023). "Specifically, colitis enhanced mRNA levels of CD86 (t7.8 = −3.2; p = 0.013) and TNF-α (t9.3 = −3.4; p = 0.006), did not change IL-1β expression, but decreased Nos2 expression (t7.092 = 5.237; p = 0.001)." (PMID 31882991, 2019).
glioma (34 papers, 2009 to 2025). A benign or malignant brain and spinal cord tumor that arises from glial cells (astrocytes, oligodendrocytes, ependymal cells). "However, NOS2 expression is up-regulated and associated with poor outcome in many human cancers, such as melanoma, glioma and colon cancer." (PMID 22971289, 2012). "Aberrant nitric oxide synthase 2 (NOS2) expression and its enzymatic product nitric oxide (NO), which play a crucial role in the pathophysiology of several inflammatory disorders, have been implicated in the development, growth and progression of several human malignant tumors, including glioma." (PMID 30227679, 2018). "During the past decade, a significant proportion of cancers have demonstrated elevated NOS2 expression, where cancers ranging from melanoma to glioma overexpress NOS2." (PMID 37169743, 2023). "NO produced by iNOS or NOS2 in glioma displays cytoprotective properties at low physiological levels, while producing toxic effects at high concentrations at high levels." (PMID 37759870, 2023). "In glioma C6 cells, 300 μM Mn treatment for 24 h activates the NF-κB pathway and enhances NOS2 expression." (PMID 38132161, 2023). "There is research conducted in C6 glioma cells indicating that NF-kB modulation is significant to Nos2 regulation." (PMID 36010960, 2022). "Studies also revealed that lower amount of nitric oxide (NO) produced through inducible nitric oxide synthase (iNOS/NOS2) in various tumors, including gliomas, can promote angiogenesis, invasion, and cellular proliferation." (PMID 34084145, 2021). "This study demonstrated that inhibition of miR-454-3p in glioma cells promoted M2 macrophage polarization, corresponding to elevated expression of II1b, Cd86, and Nos2, and reduced expression of Cd163, Ym1 and Mrc1 in macrophages." (PMID 33363140, 2020). "A total of 496 patients (with 362 gliomas including 176 glioblastomas and 134 meningiomas) were included in the study (see Section 2.3.5 and Section 2.4.8 “Brain Tumors” regardingNOS1 and NOS2)." (PMID 32111088, 2020). "In this regard, previously, our findings evidenced a significant upregulation of NOS2 in glioma cells grown in specific conditions to promote the GSC expansion as three-dimensional (3D) sphere cultures (neurospheres, NS)." (PMID 31226744, 2019). "NOS2 protein resulted in overexpressed neurospheres generated by the primary glioma cells after 20 days of culture in GSC-M as compared to relative adherent cells cultured in St-M." (PMID 30227679, 2018). "The key roles of NOS2 in tumor development and vessel maturation in the C6 rat glioma cell line were also published." (PMID 30227679, 2018). "High NOS2 expression in glioma tissue specimens correlates with decreased survival in human glioma patients." (PMID 30279357, 2018). "The clonogenic potential of U-87 MG treated daily with 1400W for 10 days was significantly lower (p < 0.0001) than that in the control group, which indicated the crucial role of NOS2 activity on the capacity of the glioma cell line to produce progeny." (PMID 30227679, 2018). "GSCs have been shown to express high NOS2 levels, which were correlated with a poorer glioma patient survival." (PMID 30227679, 2018). "NOS2 was confirmed to be expressed in both the glioma cell line and a human glioma primary culture, and overexpressed in relative derived neurospheres." (PMID 30227679, 2018). "The aim of the present work was to evaluate the effect of 1400W, a specific NOS2 inhibitor, on human glioma cells in terms of clonogenic potential, proliferation, migration rate, and neurosphere generation ability." (PMID 30227679, 2018). "Fractionated radiotherapy has been reported to increase SOX2 and Notch expression through NOS2/NO system upregulation, leading to glioma resistance to radiotherapy." (PMID 30227679, 2018). "As recently reviewed, an overexpressed NOS2/NO system in the tumor cell induces invasion, angiogenesis, immunosuppression, differentiation, and therapeutic resistance in gliomas." (PMID 30227679, 2018).